IRS1 (insulin receptor substrate 1)
Diseases named in the same sentence as IRS1 in open-access papers (continued):
Sharing a sentence is not in itself a finding about the gene and the disease.
Insulin resistance (continued). "Thus, TNF-α and SOCS3 require an active serine 307 phosphorylation site on IRS-1 to bring about insulin resistance." (PMID 25352752, 2014). "In addition to stimulating muscle anabolism, activated mTORC1/S6K1 can phosphorylate insulin receptor substrate 1 (IRS‐1) on serine residues, which can lead to insulin resistance." (PMID 24997070, 2014). "For example, high-dose leucine infusion and supplementation have been shown to induce insulin resistance and glucose intolerance in both human and animal models, possibly via activation of mammalian target of rapamycin- (mTOR-) insulin receptor substrate 1 (IRS-1) signaling pathways." (PMID 25400942, 2014). "The intestinal ME1-directed liver phenotype was accompanied by increased hepatic IRS1 activation in Tg mice, consistent with the development of whole body insulin resistance and with increased mRNA expression of Protein Kinase C-ε, known to be associated with hepatic insulin resistance." (PMID 25402228, 2014). "Furthermore, GGDGT ameliorated insulin resistance by decreasing plasma levels of insulin, improving glucose tolerance, and restoring insulin signalling by recovery of IRS-1 expression in skeletal muscle tissues." (PMID 25416139, 2014). "Finally, the Ser307 phosphorylation of IRS-1 through TNF-α induced JNK signaling results in insulin resistance." (PMID 24481061, 2014). "In addition, we have previously shown that oxidative stress induces further insulin resistance through tyrosine nitration of insulin receptor substrate-1, resulting in reduced glucose disposal." (PMID 25407968, 2014). "Impaired tyrosine phosphorylation of IRS-1 is correlated with insulin resistance in vivo." (PMID 24481061, 2014). "Furthermore phosphorylation on three important Ser residues 984, 1037, and 1101 in C-terminal of IRS-1 also has been shown to induce insulin resistance." (PMID 25580119, 2014). "DUSP9 over-expression in genetically obese ob/ob mice on the other hand, improved glucose tolerance, while DUSP9 over-expression in 3T3-L1 adipocytes suppressed ERK1/2 and JNK activation, with a concomitant reduction in IRS1 serine phosphorylation that prevented the induction of insulin resistance." (PMID 25375135, 2014). "However, the dynamics of mTORC1/S6K1 effect on IRS‐1 serine phosphorylation and insulin resistance remains to be examined." (PMID 24997070, 2014). "Therefore, we examined the effects of triterpenoid saponins on the activities of the AMPK, IR/IRS-1/PI3K/Akt signaling pathways in an in vitro model of hepatic insulin resistance." (PMID 24918297, 2014). "AC6 improved insulin sensitivity through the enhancement of insulin action on insulin receptor substrate-1 (IRS-1) associated phosphoinositide 3-kinase (PI3-kinase) and glucose transporter type 4 (GLUT4) activities in the muscles of animals exhibiting insulin resistance." (PMID 25396726, 2014). "To determine whether dietary carbs are necessary for HFD to induce insulin resistance in metabolically active tissues, we examined the levels of serine phosphorylation of IRS1 and phosphorylation of Akt in liver and gastrocnemius." (PMID 25055153, 2014). "Furthermore, phosphorylation on Ser-1101 by S6K1 on C-terminal of IRS-1 is thought to be involved in blocking tyrosine as well as AKT phosphorylation that leads to insulin resistance in mice as well as in human." (PMID 25580119, 2014). "There is no doubt that exposure to excess insulin can cause global insulin resistance through a feedback loop that includes tyrosine-phosphorylated IRS1/2, PI3K, Akt, mTOR, S6K, and serine-phosphorylated IRS1/2." (PMID 24741073, 2014). "Additionally, GSK3β mediating high glucose-induced ubiquitination and proteasome degradation of IRS1 enhances insulin resistance." (PMID 25089247, 2014).
Insulin resistance (continued). "Our data suggest evodiamine improves glucose tolerance and prevents progress of insulin resistance associated with obese/diabetic states, at least in part, through AMPK activation followed by inhibition of mTOR-S6K signaling and IRS1 serine phosphorylation in adipocytes." (PMID 24391749, 2013). "Thus, LPS induce S-nitrosation/S-nitrosylation of the insulin signaling pathway (IR, IRS-1, and Akt), inducing insulin resistance in the liver, muscle, and adipose tissue in a more particular way than serine phosphorylation of IRS-1." (PMID 23840101, 2013). "ROS have been hypothesized to inhibit the cell signaling of the insulin receptor by blocking the pathway between insulin-receptor substrate 1 (IRS-1) and phosphatidylinositol-4,5-bisphosphate 3-kinase, thereby inducing insulin resistance (IR)." (PMID 24191253, 2013). "Several reports have studied the modification effect of T2D genetic variations, IRS1 (rs2943641) and GIPR (rs2287019) on weight loss and related improvement of insulin resistance in a 2-year randomized trial: the Preventing Overweight Using Novel Dietary Strategies (POUNDS LOST) trial." (PMID 23997649, 2013). "A key mechanism by which TNF-α induces insulin resistance involved phosphorylation of IRS-1." (PMID 24455420, 2013). "At later time points (6, 12, and 24 h) insulin was not able to increase IRS-1 tyrosine phosphorylation, indicative of insulin resistance, although this effect is partially explained by an LPS-induced increase in basal IRS-1 tyrosine phosphorylation (6 and 12 h)." (PMID 23704966, 2013). "In addition, reduction of insulin receptor substrate 1 (IRS1) serine phosphorylation, an indicator of insulin resistance, was detected in their WAT, suggesting suppression of the negative feedback loop from S6K to IRS1." (PMID 24391749, 2013). "The activity of Jun NH2-terminal kinase (JNK) protein is significantly elevated in various tissues in T2DM patients and animal models, which can impair insulin signaling transduction and lead to insulin resistance through activating the serine phosphorylation of insulin receptor substrate-1 (IRS-1)." (PMID 23829668, 2013). "Because the IRS1 serine 307-kinase catalyzes a critical step in the control of insulin signaling and constitutes a potential target for treatment of insulin resistance, it is important to know whether S6K1 is the physiological serine 307-kinase or not." (PMID 23565163, 2013). "Phosphorylation of IRS1 at Ser307 is of interest as it has been implicated in a causative mechanism of insulin resistance, as part of negative or positive control signals." (PMID 23565163, 2013). "Besides IRS1 rs2943634 the group of insulin resistance SNPs consisted of PPARG rs1801282, GCKR rs780094, GCKrs1799884, and IGF1rs35767." (PMID 23101478, 2012). "Tumor necrosis factor (TNF), a pro-inflammatory cytokine with a major pathogenetic role in RA, may promote insulin resistance by inducing Ser312 phosphorylation (p-Ser312) of insulin receptor substrate (IRS)-1 and downregulating phosphorylated (p-)AKT." (PMID 22691241, 2012). "Recently, it has been demonstrated that increased lysophosphatidylcholine content, a phosphatidic acid, in L6 myotubes treated with palmitate also leads to JNK activation and IRS-1 Ser307 phosphorylation, contributing to the development of muscle insulin resistance." (PMID 22360800, 2012). "This study tested the hypothesis that IRS1 cells expression can be used as insulin resistance (IR) marker in HCV-infected patients." (PMID 22830036, 2012). "Resistin also phosphorylates IRS1 through mTOR to promote insulin resistance." (PMID 22545721, 2012). "However, the observation of decreased IRS-1 tyrosine phosphorylation is consistent with insulin resistance." (PMID 22629383, 2012).
Insulin resistance (continued). "In conclusion, selected treatment-naïve, nonobese, noncirrhotic, nondiabetic patients with HCV presented a lower expression of IRS1 both in leukocytes and in the liver, and this may be related to the commencement of insulin resistance." (PMID 22830036, 2012). "Based on our findings of improved insulin resistance in patients with active RA following treatment with anti-TNF agents, we examined whether this effect is associated with altered IRS-1 phosphorylation." (PMID 22691241, 2012). "Another mechanism of insulin resistance involves the serine phosphorylation of IRS-1." (PMID 23272222, 2012). "Elevated oxidative stress induces insulin resistance by impairing phosphorylation of insulin receptor substrate (IRS)-1 and IRS-1-induced phosphatidylinositol 3 (PI3)-kinase activation, insulin-induced glucose uptake, and translocation of glucose transporter (GLUT)-4." (PMID 22778500, 2012). "Participants with the IRS1 rs2943641 CC genotype had greater weight loss and improvement of insulin resistance than those without this genotype in response to a high-carbohydrate/low-fat diet." (PMID 24392269, 2012). "IRS1 and PPARGC1A belong to the small group of T2D susceptibility genes which might mediate their effects through insulin resistance and therefore be relevant in peripheral tissues such as SAT and skeletal muscle." (PMID 23251491, 2012). "Serine phosphorylation of IRS-1 (insulin receptor substrate-1) has been suggested as a mechanism for TNF-α-mediated insulin resistance and modulated the activity of the key regulatory enzyme of androgen biosynthesis, P450c17 in the adrenal and ovarian steroidogenic tissues." (PMID 22778733, 2012). "It is known that angiotensin II can both contribute to oxidative stress-induced insulin resistance, and directly result in serine phosphorylation of IRS-1, but the specific kinases involved and the role of this hormone on human models of insulin resistance have yet to be determined." (PMID 21589939, 2011). "S6K1/IRS-1 feedback has been shown to be important in insulin resistance and cancer." (PMID 22102801, 2011). "In summary, we observed that insulin resistance in the non-obese population is associated with an activation of the JNK pathway with increased serine phosphorylation of IRS-1." (PMID 21589939, 2011). "Research findings have suggested that these up-regulated miRNAs may be translational repressors of IRS-1 expression, and that they may be involved in the development of insulin resistance." (PMID 21464990, 2011). "The role of JNK in insulin resistance has been further highlighted by its interaction with IRS-1." (PMID 20508722, 2010). "Hepatic insulin resistance represents a paradox in hepatic steatosis since insulin receptor activation of insulin receptor substrate-1 (IRS-1) is active and accounts for increased DNL, yet insulin does not inhibit insulin receptor substrate-2, which controls liver gluconeogenesis." (PMID 20300478, 2009). "The data demonstrated an interaction between testosterone and insulin on phosphorylation of intracellular signaling proteins, and suggests a link between a hyperandrogenic, hyperinsulinemic environment and the development of insulin resistance involving serine phosphorylation of IRS-1 Ser636/639." (PMID 19169352, 2009). "Mice deficient for Irs-1 develop insulin resistance but do not progress to diabetes because they maintain normal pancreatic β-cell numbers." (PMID 19534786, 2009). "Studies indicate that insulin resistance can be induced by stimulating the degradation of important molecules in the insulin signaling pathway, in particular the insulin receptor substrate proteins IRS1, IRS2 and the kinase AKT1 (Akt)." (PMID 19007436, 2008). "IRS-1 knock out (Irs1-/-) female mice show increased lifespan despite moderate insulin resistance." (PMID 19412415, 2007).
Insulin resistance (continued). "Since we have depicted the highly prevalence of AGT and insulin resistance in these PCOS affected patients, it suggests that these two IRS-1 polymorphisms are unrelated to the emergence of glucose dysmetabolism and insulin resistance in PCOS for the Taiwanese Hoko and Hakka population." (PMID 16603055, 2006). "Together, these findings indicate that SAA promotes insulin resistance through receptor-mediated mechanisms, most likely involving NF-κB-driven disruption of the IRS-1/PI3K/Akt signaling cascade, a hypothesis that requires validation in clinical settings to establish its translational relevance." (PMID 41313351, 2026). "Existing literature proposes that Yerba Maté polyphenols could potentially modulate hepatic insulin signaling by suppressing TNF-α, and may interact with the PI3K-AKT pathway, involving elements like Akt2 and Irs1, possibly contributing to improved peripheral insulin resistance." (PMID 41244043, 2025). "Excessive dietary iron might have induced systemic iron overload (IO), which triggers oxidative stress-mediated mitochondrial damage and impairs IRS-1 signaling through serine phosphorylation, fostering insulin resistance and hepatic inflammation —key drivers of MetS pathogenesis." (PMID 41156438, 2025). "Furthermore, mice subjected to a high-fat diet exhibited reduced levels of Atg16L1 and IRS1 in epididymal white adipose tissue, suggesting that insulin resistance may result from diminished expression of Atg16L1, leading to the subsequent degradation of IRS1." (PMID 41439967, 2025). "Therefore, exercise can improve peripheral insulin resistance through the IRS1/PI3K/AKT/GLUT4 pathway, which may be effective in ameliorating the progression of DKD." (PMID 39526249, 2024). "Therefore, in this study, PA may alleviate a HFD-induced insulin resistance by inhibiting the IRS1 phosphorylation pathway." (PMID 39064674, 2024). "Furthermore, KA decreased glycerol kinase (GK) expression and increased insulin receptor subtrate 1 (IRS-1) and IRS-2 expressions in the WAT of DIO mice, suggesting that KA partially improved insulin resistance by repairing the impaired insulin signaling pathway caused by DIO." (PMID 38655315, 2024). "Single nucleotide polymorphisms (SNPs) in genes involved in insulin resistance have also been described in individuals with MASLD, including the genes of “ectoenzyme nucleotide pyrophosphate phosphodiesterase 1” (ENPP1 or PC1) and “insulin receptor substrate-1” (IRS1)." (PMID 38891828, 2024). "Furthermore, we identified myocardin downregulation as a key mechanism of cardiac insulin resistance mediated by decreasing IRS-1 expression, highlighting the therapeutic potential of upregulating myocardin activity for lipodystrophy cardiomyopathy and insulin resistance-related HF." (PMID 38505620, 2024). "In addition, the downregulation of IRS-1 expression can induce systemic insulin resistance." (PMID 38681139, 2024). "While phosphorylation of IRS1 at S307 has been linked to insulin resistance, whether it is part of a negative or positive feedback loop that controls insulin signaling remains controversial and could be tissue-dependent." (PMID 38029396, 2024). "This activity is enforced at the higher dose of CPF since the increased levels of p-IRS1 Ser 302 phosphorylation, usually part of the physiological feedback mechanism involved in silencing the insulin receptor signaling deregulated, indeed, in insulin resistance." (PMID 37298533, 2023). "Burn injury stimulates insulin production and produces insulin resistance in liver, skeletal muscle, and adipose tissue, associated with post-receptor alterations such as phosphorylation of the insulin receptor substrate-1 (IRS-1) in the absence of changes in insulin receptor binding." (PMID 37333522, 2023). "Moreover, CRP impairs insulin receptor substrate 1 (IRS-1) which might explain the state of insulin resistance in obesity due to elevated CRP levels." (PMID 36520252, 2023).
Insulin resistance (continued). "This may be a result of high fructose consumption, as it has been reported that fructose-1-phosphate activates mitogen-activated protein kinase, which phosphorylates insulin receptor substrate 1 at the serine residue, leading to hepatic insulin resistance (IR)." (PMID 37261280, 2023). "The restoration of IRS-1 expression and the downregulation of insulin resistance markers highlight the potential of hesperidin as a promising therapeutic intervention to counter the negative impact of liver insulin resistance caused by IL-6." (PMID 38234970, 2023). "Additionally, flavonoids could suppress GLUT4 translocation or inhibit IRS-1 signaling to reduce protein degradation when insulin resistance was elevated." (PMID 36677745, 2023). "Similarly to our observations, decreased SHBG mRNA and protein levels have been previously correlated to lower expression of insulin-associated effectors, namely, IRS-1, IRS-2, PI3Kp85α and GLUT-3 and GLUT-4, and has been further linked to the PI3K/AKT pathway-mediated systemic insulin resistance." (PMID 38146533, 2023). "Metformin may inhibit the release of calpain 2 from exosomes, interfere with IR splitting (through the pathway of knocking out calpain 2 and γ-secretase), restore the functions of IRS-1 and Akt, and re-establish insulin signaling, thereby alleviating insulin resistance, enhance insulin sensitivity." (PMID 36818396, 2023). "As mentioned, augmented SUA levels may lead to oxidative stress, which then may impair glucose metabolism and reduce insulin sensitivity, and might contribute to insulin resistance by upregulating insulin receptor substrate 1 phosphorylation, as well as increased production of excessive ROS." (PMID 37671195, 2023). "Several protein kinase C (PKC) isoforms are involved in saturated fatty acid (SFA)-mediated insulin resistance; for example, IR down-regulation accompanied overexpression of PKCε and insulin receptor substrate-1 (IRS-1) inactivation could arise from PKCδ-induced serine phosphorylation." (PMID 36718668, 2023). "This association has been studied in males, where Ang II was found to increase phosphorylation of IRS-1 and inhibit insulin-stimulated activation of eNOS, suggesting that Ang II may be the link between insulin resistance and the development of vascular cell dysfunction." (PMID 38025203, 2023). "In addition, our previous studies verified that the activation of PPARγ could alleviate obese insulin resistance with the IRS-1 insulin metabolic pathway in vivo and in vitro." (PMID 37049846, 2023). "IRS-1 regulation differs in the liver as it has been observed in diabetic animals, which may result in distinctive changes in insulin levels in liver tissue and contribute to insulin resistance in liver." (PMID 37089941, 2023). "The AKT genes and IRS1 may influence adipocyte insulin resistance." (PMID 37680885, 2023). "Additionally, the decreased phosphorylation of IRS1 increased expression of PPARγ and reduced phosphorylation of NF-κB could be attributed to the attenuation of insulin resistance of vitamin D3." (PMID 37324274, 2023). "Additionally, an increase in miR-143-3p and subsequent inhibition of insulin receptor substrate 1 (IRS1) may lead to the initiation of NASH via the development of insulin resistance and hyperglycemia in the liver." (PMID 36612019, 2022). "In addition, hypertrophic adipocytes are more prone to necrosis, which increases local inflammation in adipose tissue via serine phosphorylation of insulin receptor substrate-1 via nuclear factor κB and Jun N-terminal kinase signaling, leading to the development of insulin resistance." (PMID 35888573, 2022). "Thus, a lowered IRS-1 protein alone in the muscle of OZRs might trigger the progression of insulin resistance since this defect would diminish downstream insulin signaling to cause a reduction in glucose disposal." (PMID 36547071, 2022).